CD4 (CD4 molecule)
Diseases named in the same sentence as CD4 in open-access papers (continued):
Sharing a sentence is not in itself a finding about the gene and the disease.
esophageal cancer (48 papers, 2013 to 2025). A primary or metastatic malignant neoplasm involving the esophagus. "Meanwhile, the expressions of PD-1 and TIM-3 on CD4+ T cells were closely associated with clinic pathological features of esophageal cancer patients." (PMID 27577071, 2016). "This convergence of evidence highlights the critical role of CD4+ T cells in particular in the adaptive immune response against esophageal cancer, which is consistent with our work." (PMID 41473739, 2025). "Immunohistochemical staining of esophageal cancer patient samples showed a lower percentage of CD4+ cells in the galectin 7 high area." (PMID 38503797, 2024). "Immunohistochemical staining of samples from esophageal cancer patients showed that galectin 7 expression level was negatively correlated with the percentage of CD4+ T cells." (PMID 38503797, 2024). "Through the analysis of TIMER database, we found that FOXP1 expression is significantly positively correlated with B cell, CD4 + T cell, and macrophage expression level in oesophageal cancer." (PMID 38652109, 2024). "Concurrent with the given history of PSP, other researchers have shown its potentiality with gastral and esophageal cancers due to its characteristics of showing a superior CD4+ and CD8+ cell count among other treatments." (PMID 36992512, 2023). "In general, high factions of activated memory CD4+ T cells were correlated with good survival in esophageal cancer, which as opposite to our findings." (PMID 36619388, 2022). "In oesophageal cancer, it was also found that a high proportion of CD4+CD8+ (>3.45%) cells and a low proportion of regulatory T cells (≤5.15%) before chemoradiotherapy were related to a better OS." (PMID 36451825, 2022). "In conclusion, vaccination with the CPV S-588410 induces functional CD8+ and CD4+ TILs and PD-L1 expression in esophageal cancer." (PMID 32500232, 2020). "Using the TIMER database, we found that FGL2 expression correlated positively with the levels of immune markers of infiltrating B cells, CD8+ T cells, CD4+ T cells, macrophages, neutrophils and dendritic cells in esophageal carcinoma samples." (PMID 33323552, 2020). "It was also significantly higher than that of CD4+ PBMCs from esophageal cancer patients (76.83 ± 2.565% vs. 62.80 ± 2.882%, p < 0.0001; 62.80 ± 2.882% vs. 35.75 ± 35.75%, p = 0.0001)." (PMID 27577071, 2016). "The percentage of CD4+ TILs expressing BTLA was significantly lower than that of circulating CD4+ T cells from esophageal cancer patients (91.73 ± 0.7573% vs. 95.46 ± 1.438%, p = 0.0199)." (PMID 27577071, 2016). "High levels of CD8+ cytotoxic T cells and low levels of CD4+ regulatory T cells in the tumor microenvironment have been shown to positively correlate with a favorable clinical outcome in esophageal carcinoma." (PMID 27959959, 2016). "Reversed CD4+/CD8+ ratios due to reduced percentage of CD4+ T cells have been reported in patients with colon, gastric, and esophageal cancers; however, studies on other types of cancer have found normal CD4+/CD8+ ratios [-]." (PMID 25605488, 2015). "Also, there is a correlation between HIF1A and immune cells (B cell, CD8+ cell, CD4+ cell, macrophage, neutrophil, or dendritic cell) in esophageal carcinoma, stomach adenocarcinoma, colon adenocarcinoma, and rectum adenocarcinoma." (PMID 39928794, 2025). "In esophageal carcinoma (ESCA), GPX4 expression was significantly associated with the infiltration of macrophage and myeloid dendritic cell, and AIFM2 expression was significantly associated with the infiltration of CD4+ T cell." (PMID 34722530, 2021). "Moreover, lower CD3+, lower CD4+ and lower CD4+/CD8+ ratio were factors independently associated with worse prognosis of esophageal cancer patients in different reports." (PMID 23575450, 2013).
esophageal cancer (continued). "Therefore, our study suggests that the reduced expression of FOXP1 in oesophageal squamous cell carcinoma may lead to downregulation of CD4+ T cells and B cells, promoting immune escape of tumour cells and progression of oesophageal cancer." (PMID 38652109, 2024). "Moreover, there was a strong positive correlation between HNF1B expression and CD4+ T cell levels in esophageal carcinoma (ESCA, r = 0.317, p =1.45e-5), Uterine Carcinosarcoma (UCS, r = 0.338, p =1.32e-02), liver hepatocellular carcinoma (LIHC, r= 0.451, p = 1.02e-18)." (PMID 33173410, 2020). "The Streptococcus genus enhances the antitumor immune response by increasing the infiltration of CD4+ CXCL13+ T cells, and the presence of Streptococcus in esophageal cancer can predict the response to anti‐PD‐1 therapy." (PMID 41346571, 2025). "The MFI of BTLA on CD4+ and CD8+ TILs was lower than that of circulating CD4+ and CD8+ T cells from esophageal cancer patients." (PMID 27577071, 2016). "We examined the correlations between PD-1 and TIM-3 or TIGIT expression in CD4+ and CD8+ T cells in PBMC (n = 35), AEM (n = 25) and tumor tissues (n = 25) from esophageal cancer patients." (PMID 27577071, 2016). "We showed that the expressions of PD-1 and TIM-3 on circulating CD4+ and CD8+ T cells from esophageal cancer patients (n = 35) were significantly higher than that from normal donors (n = 10)." (PMID 27577071, 2016). "We next assessed the expressions of PD-1, TIM-3, TIGIT and BTLA on CD4+ and CD8+ T cells isolated from esophageal cancer tissues, adjacent esophageal mucosa (AEM), and peripheral blood mononuclear cell (PBMC) from esophageal cancer patients." (PMID 27577071, 2016). "Immunohistochemical staining of esophageal cancer patient samples also showed a negative correlation between galectin 7 expression and the percentage of CD4+ T cells." (PMID 38503797, 2024). "In addition, S-588410 administration in a pre-surgical study on esophageal cancer has also shown to induce functional CD8 + and CD4 + TILs, specifically CD8 + PD-1 + and CD4 + PD-1 + cells." (PMID 38990441, 2024). "Moreover, the expression levels of GPR84 were remarkably higher in purified MDSCs than in purified CD4+ and CD8+ T cells from esophageal cancer tissues, suggesting that GPR84 was specifically highly expressed on MDSCs in patients with ESCC." (PMID 37105980, 2023). "Statistically significant (p < 0.001) decreases in Tregs (CD3 + CD4 + CD25 + CD127low/−) were observed at 6, 168, and 336 h, as predicted based on data from a phase I study of single-agent mogamulizumab in patients with CCR4− lung and esophageal cancers." (PMID 31801624, 2019). "A preclinical study on esophageal cancer showed that CAFs may block the infiltration of CD8+ T cells and increase the infiltration of CD4+ Treg through IL-6, and targeting CAFs can improve the existing tumor immunity and enhance the efficacy of conventional immunotherapy." (PMID 36685566, 2022). "Interestingly, esophageal cancer patients with late stage tumors harbor a greater density of regulatory T cells (CD4+CD25high) in their peripheral blood as opposed to early stage cancers." (PMID 32298379, 2020). "The results of this study suggest that the CD3 and CD4 levels and CD4-to-CD8 ratios of both patient groups were lower than the normal values, indicating that cellular immune function was low in patients with esophageal cancer before surgery." (PMID 36451459, 2022). "Another study found that a high CD8+/CD4+ ratio and a low FOXP3/CD8 ratio correlate with prolonged survival of PD-L1+ patients but not for that of PD-L1− patients with esophageal cancer." (PMID 34797860, 2021). "Furthermore, a high CD8+/CD4 + ratio and low FOXP3/CD8 ratio correlate to longer survival of stromal PD-L1 + patients, but not that of stromal PD-L1 − patients with esophageal cancer." (PMID 38233811, 2024).
brain tumors (47 papers, 2013 to 2026). "PTEN HemDel in brain tumors was linked to higher CD4 T memory cells and M2 macrophage abundance and lower M1 macrophages, monocytes, and CD8 T cells." (PMID 36977733, 2023). "The mechanism of action was associated with a decrease in the frequency of brain tumor-infiltrating CD4+CD25+ T cells, while simultaneously eliminating their suppressor activity." (PMID 23720663, 2013). "There were more CD4+ T cells found in the spleen and particularly in the brain tumor of mice transferred with M002-treated CD4+ T cells than in mice given saline-treated CD4+ T cells." (PMID 39885128, 2025). "Given the highly specialized immune environment of the brain, data on CD4+ T cell composition in the brain tumor microenvironment is limited." (PMID 40346687, 2025). "ZIKV-induced brain tumour immune cell infiltration includes CD4+ T cells, CD8+ T cells, NK cells, monocytes, macrophages, DCs and microglia." (PMID 40240536, 2025). "As ApoE-CaCP efficiently increased CD8+ and CD4+ T cells in blood circulation, we continued to analyze T-cell infiltration in brain tumors." (PMID 36702831, 2023). "The frequency of CD3+/CD4+ helper T cells in the peripheral blood of all patients with different malignant brain tumor entities was lower than that in the healthy control cohort." (PMID 38137456, 2023). "This has been demonstrated by flow cytometric analysis, showing that FasL levels expressed in the endothelium of brain tumors are inversely correlated with the CD8+/CD4+ TIL ratio." (PMID 35464435, 2022). "We found that the frequencies of IFN-γ-, TNFα-, and IL-2-producing CD4+ T cells were increased in the brain tumour, spleen, and blood of EMP3_KO model mice." (PMID 33964937, 2021). "When we evaluated the percentages of IFN-γ-, TNF-α-, and IL-2-producing CD4+ and CD8+ T cells within GBM tumours, we noticed that CXCR3 blockade in the EMP3_KO group reduced CD8+ and CD4+ T cell infiltration into the brain tumour, blood, and spleen." (PMID 33964937, 2021). "ISV+α-CTLA-4 increased CD8+ and CD4+ T cells in flank and brain tumors compared with untreated mice." (PMID 32690669, 2020). "In high grade brain tumors, Tregs suppress activation, proliferation and cytokine production of CD4+/CD8+ T cells via secreted cytokines such as TGF-B and IL-10 or via cell-to cell contact mediated by the constitutively expressed CTLA-4 and PD-L1 checkpoints." (PMID 30974896, 2019). "CD8+ and CD4+FoxP3+ T cells were revealed by immunofluorescent staining of brain tumor cryosections and quantitated using Fiji software." (PMID 31462642, 2019). "Analysis of T cell subsets in brain tumor revealed that infiltrating CD4+ and CD8+ T cells expressed CD57." (PMID 31417550, 2019). "In this study, we used A20HA cells as a brain tumor experimental model to evaluate immunomodulatory effects of a brain lymphoma on adoptively transferred HA-specific CD4+ T cells." (PMID 24693228, 2014). "Overall, our study firmly establishes the benefit of incorporating tumour specific CD4 T cells in adoptive cell therapies for brain tumours." (PMID 23717511, 2013). "Overall, we demonstrate that the inclusion of tumour antigen specific CD4 T cells for adoptive immunotherapy of brain tumours is more efficacious than transferring an equivalent number of CD8 T cells alone." (PMID 23717511, 2013). "In addition, preclinical data showed increased CD4+ cells and resistance to Treg‐mediated suppression within the brain tumors in mice receiving immunotherapy." (PMID 36866788, 2023). "Primary and secondary brain tumors are infiltrated with CD4+ CD25+ Foxp3+ T regulatory cells." (PMID 31244853, 2019). "We have established survival rate of A20HA brain-tumor-bearing mice and demonstrated possibility of adoptively transferred CD4+ T cells to the tumor-specific activation in vivo as well as development of the tumor-specific anergy in process of the brain tumor progression." (PMID 24693228, 2014).
brain tumors (continued). "The activated HA-specific CD4+ T cells were found also in the brain of brain-tumor-bearing mice." (PMID 24693228, 2014). "We investigated whether in vitro Th1 and Th2 polarisation could generate CD4 T cells with functional properties useful for adoptive therapy of brain tumours." (PMID 23717511, 2013). "Next, we used the Brain Tumor Immune Micro Environment (TIME) dataset to analyze the expression levels of these 5 genes in CD45– GBM cells and tumor-associated immune cells (e.g., BMDMs, microglia, neutrophils, CD4+ T cells, and CD8+ T cells) isolated from human GBM tumors." (PMID 40626360, 2025). "Imbalance of peripheral T cell subsets (decreased CD8+ and increased CD4+ cells) has been reported in AD patients indicating peripheral immune response in AD; this is similar to a previous report on brain tumor patients that showed altered peripheral immune parameters in patients with a brain tumor." (PMID 28790893, 2017). "However, our data, at least for brain tumours, suggests that optimal benefit from CD4 T cells will be achieved by choosing a tumour-expressed antigen, which will ensure antigen-specific restimulation of the CD4 T cells at the tumour site." (PMID 23717511, 2013). "When we represented the immune signature for each brain tumor type, we found that CD8+ T cell and resting memory CD4+ T cells were more abundant than other lymphocytes, and M2 macrophages were more abundant than other myeloid cells (one-way ANOVA, p < 0.0001)." (PMID 38540119, 2024). "That is, FasL expression indicates not only the CD8+/CD4+ TIL ratio, but also the tumor contribution by immune avoidance in brain tumors due to decreased T cell presence." (PMID 35464435, 2022). "Rindopepimut (Rintega®, Celldex Therapeutics, Inc., Phillipsburg, NJ, USA), a 14-mer injectable peptide vaccine against EGFRvIII, was projected to activate CD4+ and CD8+ T cells against malignant brain tumor cells." (PMID 33803885, 2021). "In contrast to the long-term dogma that defined the brain as an immune-privileged organ, the presence of primary or secondary brain tumors correlates with a significant infiltration of CD8+ and CD4+ T cells." (PMID 31244853, 2019). "The potential of combined CD4 and CD8 T cell transfer in brain tumour immunotherapy was previously highlighted in an intracranial fibrosarcoma model, although polarisation status was not studied." (PMID 23717511, 2013). "Using tissue microarrays of 158 brain tumour samples, we assessed CD3, CD4, CD8, CD20, CD138, Granzyme B (GzmB), 5-Lipoxygenase (5-LOX), Programmed Death-Ligand 1 (PD-L1), O-6-Methylguanine-DNA Methyltransferase (MGMT) and Transglutaminase 2 (TG2) expression by immunohistochemistry (IHC)." (PMID 38816839, 2024). "At the level of the lymphoid compartment, the sequestration of T cells in the bone marrow of patients with brain tumors was previously reported, and could explain the lower number of CD8 and CD4 T cells." (PMID 38753169, 2024). "For example, whereas the density of CD4+Foxp3+ T-cells in the carcinoma areas exhibited a positive correlation with survival after brain tumor resection, their density in stromal areas did not." (PMID 34647108, 2021). "Both CD4 and CD8 cells are essential in the rejection of brain tumors by combinatorial HSC + PD-1." (PMID 30333482, 2018). "Though the schematic diagram also shows interactions between brain tumor and the immune system, namely, macrophages, CD8+ T-cells, CD4+ T-cells, TGF-β, IFN-γ, microglial cells, dendritic cells etc., we have kept our model simple by choosing only five state variables." (PMID 25955428, 2015). "Moreover, tumour-antigen specific Th1 CD4 T cells enhanced CD8 T cell recruitment and function within the brain tumour bed." (PMID 23717511, 2013).
brain tumors (continued). "Collectively, these data clearly demonstrate that the EphA3 CAR expressed in primary human CD4+ and CD8+ T cells, whereby it can function in an antigen-dependent manner to signal to induce activation, cytokine secretion, and exert cytotoxic effect on target brain tumor cell lines." (PMID 39111833, 2024). "However, infiltration of brain tumors by CD8+ and CD4+ T cells has been observed." (PMID 39469707, 2024). "Interestingly, the report also showed successful visualization of CD4+ T cell infiltration in a humanized brain tumor mouse model compared to no brain uptake in the non-disease control group." (PMID 35733858, 2022). "We also evaluated the percentages of CD8+ and CD4+ T cells within the tumour, blood, and spleen and found that anti-PD-1 treatment of EMP3_KO tumour-bearing mice increased IFN-γ-, TNF-α- and IL-2-producing CD8+ and CD4+ T cell infiltration into the brain tumour, blood, and spleen." (PMID 33964937, 2021). "While brain tumors treated with anti-GITR (2a) did not have significantly lower levels of intratumoral CD4 + FoxP3+ cells relative to control, anti-GITR (2a) treatment in flank tumors did result in a significantly diminished proportion of CD4 + FoxP3+ relative to control." (PMID 27190629, 2016).